CROCC (ciliary rootlet coiled-coil, rootletin)
Description:
Major structural component of the ciliary rootlet, a cytoskeletal-like structure in ciliated cells which originates from the basal body at the proximal end of a cilium and extends proximally toward the cell nucleus (By similarity). Furthermore, is required for the correct positioning of the cilium basal body relative to the cell nucleus, to allow for ciliogenesis. Contributes to centrosome cohesion before mitosis.
Synonyms: rootletin; ROLT; CROCC1; TAX1BP2
Tractability: Antibody: its Gene Ontology location is reachable by antibodies, with high confidence. PROTAC: ubiquitination databases record sites on it; its protein half-life has been measured.
Gene: Protein-coding gene on chromosome 1 (16,740,273 to 16,972,964, forward strand). Ensembl gene ENSG00000058453.
Subcellular location: Cytoplasm, cytoskeleton, microtubule organizing center, centrosome, centriole; Cytoplasm, cytoskeleton, cilium basal body; Cytoplasm, cytoskeleton, microtubule organizing center, centrosome
Subcellular location (Human Protein Atlas): Basal body; Centrosome; Mid piece; Plasma membrane; Primary cilium transition zone
Gene Ontology:
Molecular function: protein binding; kinesin binding; structural molecule activity; actin binding; structural constituent of cytoskeleton
Biological process: centriole-centriole cohesion; centrosome cycle; intracellular protein localization; positive regulation of cilium assembly; positive regulation of protein localization to cilium
Cellular component: centriole; centrosome; ciliary basal body; extracellular exosome; ciliary rootlet; 9+2 motile cilium; photoreceptor inner segment; subapical part of cell
Genetic constraint (gnomAD): Loss-of-function variants: 178 observed, 172.99 expected, observed/expected ratio (o/e) 1.03, 90% interval 0.91 to 1.16. The synonymous counts are far from expectation, so gnomAD's model fits this gene poorly and the ratio says little. Missense variants: 2,667 observed, 2,299.9 expected, observed/expected ratio (o/e) 1.16, 90% interval 1.12 to 1.2. Synonymous variants: 1,196 observed, 980.93 expected, observed/expected ratio (o/e) 1.22, 90% interval 1.16 to 1.28.
Homologues: Orthologues: chimpanzee CROCC (99% identical), macaque CROCC (97% identical), dog CROCC (88% identical), guinea pig CROCC (87% identical), pig CROCC (83% identical), mouse Crocc (83% identical), rat Crocc (82% identical), tropical clawed frog crocc (55% identical). Paralogues in human: CROCC2 (32% identical), CEP250 (28% identical), CEP135 (12% identical), TSGA10 (7% identical).
Diseases named in the same sentence as CROCC in open-access papers:
CROCC is named in the same sentence as 19 diseases in open-access papers, as found by Europe PMC text mining. Sharing a sentence is not in itself a finding about the gene and the disease. The quoted sentences say what the papers report.
colorectal cancer (3 papers, 2022 to 2025). A primary or metastatic malignant neoplasm that affects the colon or rectum. "However recent studies identified mutations in CROCC in several unusual and very aggressive colorectal cancer subtypes, which are referred to as the rhabdoid phenotype." (PMID 36285440, 2022). "Notably, CROCC gene, which codes for an important component of the ciliary root, a structure involved in centrosome cohesion prior to mitosis, could play a pathogenic role in SS similarly to what has been observed in colorectal cancer." (PMID 40918137, 2025). "We recently found that the depletion of CROCC in BRAF-mutant colorectal cancer cells promotes the acquisition of rhabdoid features." (PMID 37239344, 2023).
lymphoma (2 papers, 2023 to 2025). A malignant (clonal) proliferation of B- lymphocytes or T- lymphocytes which involves the lymph nodes, bone marrow and/or extranodal sites. "Integration of RNA-seq and WES data revealed an abundance of genes with mutations of exclusive germline inheritance that could potentially represent risk factors for the development of this lymphoma, such as those affecting the CROCC gene." (PMID 40918137, 2025). "However, the exact roles and specific functions of FHIP2B, POMT1, TTLL3, CROCC, and CD52 in lymphoma and the molecular mechanisms of their downmodulation upon MyD88L265P expression are not yet fully understood and require further research." (PMID 36982699, 2023).
diabetic nephropathy (1 paper, 2023). "The genes that contributed to the biological relevance of diabetic nephropathy, include gene TTN (rs72646845), PI16 (rs113848006), DPY6 (rs36027551), CROCC (rs41272737), PPP1R3A (rs1799999), ZNF136 (rs140861589), HSPA12B (rs6076550), and FRMD4A (rs1541010)." (PMID 37033211, 2023).
glaucoma (1 paper, 2025). Increased pressure in the eyeball due to obstruction of the outflow of aqueous humor. "The role of CROCC in glaucoma remains to be studied; however, it may serve as a biomarker for E2 response or other neuroprotection interventions in the retina." (PMID 40076480, 2025).
growth disorder (1 paper, 2021). "Loss of function of the two other ciliary genes (CEP104 and CROCC) or TSTD2 has not been reported to be associated with a growth disorder, although CROCC has been detected at genome-wide significance for adult height." (PMID 34194391, 2021).
hepatocellular carcinoma (1 paper, 2020). A malignant tumor that arises from hepatocytes. "The downregulation of CROCC was associated with poor survival in patients with hepatocellular carcinoma after surgical resection." (PMID 33110154, 2020).
medulloblastoma (1 paper, 2019). A malignant, invasive embryonal neoplasm arising from the cerebellum. "Notably, CASC5 (kinetochore-microtubule attachment and chromosome segregation, MAPK1 (involved in proliferation, differentiation, transcriptional regulation), and CROCC (centrosome cohesion before mitosis, associated with medulloblastoma) were included in this network." (PMID 30858923, 2019).
myelodysplastic syndrome (1 paper, 2025). A clonal hematopoietic disorder characterized by dysplasia and ineffective hematopoiesis in one or more of the hematopoietic cell lines. "Based on the morphology, immunology, cytogenetics, and molecular biology of bone marrow cells, the patient was diagnosed with myelodysplastic syndrome (MDS, +8, -7, IPSS-R 5.5 points, JAK2, ROBO2, and CROCC mutations)." (PMID 40881710, 2025).
Nephropathy (1 paper, 2023). A nonspecific term referring to disease or damage of the kidneys. "While gene PI16, DPY6, FRMD4A and CROCC have not been reported to be associated with nephropathy, they have been identified in T2DM and obesity-related traits." (PMID 37033211, 2023).
cancer (6 papers, 2017 to 2023). A tumor composed of atypical neoplastic, often pleomorphic cells that invade other tissues. "Although it is unclear how CROCC mutations contribute to the formation of these aggressive cancer subtypes, they were reported to cause chromosomal instability and chromosome segregation errors, which may trigger more severe cancer progression." (PMID 36285440, 2022). "Reports have flagged the functionality of CROCC with vital roles in tumors and involvement in the expression of cytokines and cancer-related genes." (PMID 31799620, 2020). "Additionally, CROCC (TAX1BP2) has been reported to function as a tumor suppressor in various cancers; however, the role of CROCC in GBC was scarcely reported." (PMID 31799620, 2020). "Conversely, we demonstrated that only the CROCC-associated signature, which included the DNA homologous recombination factor RAD52, the tumour suppressor gene HIC1 and the repressor of the sonic hedgehog pathway TULP3, had a prognostic value in ER-negative/HER2-negative cancers." (PMID 29559730, 2018). "Fourteen of the mutated genes in this tumor are involved in metabolism (endogenous molecules as well as drugs), small molecule biochemistry, and cancer: AATF, ATF71P, CRIPAK, CROCC, CYP2A6, DOCK5, GPAT2, KRTAP4–9, LSM14A, MUC2, MYO1F, RHOQ, SUFU, and UTRN." (PMID 29259192, 2017). "Notably, CROCC and γ-tubulin were observed to colocalize in large cilia found on cancer tissues but not in normal controls." (PMID 37239344, 2023).
tumor (4 papers, 2017 to 2025). "Since CROCC gene is implicated in centrosome cohesion and disjunction, and its mutation could play a pathogenic role in SS, we decided to further validate the mutations detected by RNA-seq data also by Sanger sequencing of patient tumor and matched normal cells." (PMID 40918137, 2025). "In comparison with the inhibitor NC + si-NC group, the tumor growth rate and tumor size were observed to be decreased in the inhibitor NC + si-CROCC group (P < 0.05)." (PMID 31799620, 2020). "Our study also demonstrated that miR-33b could suppress various cellular processes such as invasion, migration, proliferation, EMT, and tumor growth of GBC through down-regulating the expression of CROCC." (PMID 31799620, 2020). "The findings suggested that miR-33b could inhibit the tumor growth in nude mice with GBC through down-regulating CROCC." (PMID 31799620, 2020). "The miR-33b up-regulation or CROCC silencing was observed to increase the level of E-cadherin but decrease the levels of N-cadherin and Vimentin, corresponding to impeded cell proliferation, migration, invasion, EMT, and tumor growth." (PMID 31799620, 2020). "No evident difference in tumor growth rate was illustrated between the inhibitor NC group and the miR-33b inhibitor + si-CROCC group (P > 0.05)." (PMID 31799620, 2020).
brain disease (1 paper, 2015). "Moreover, 10 genes (ATP1A1, ATP6V1D, C16orf45, CROCC, KLC1, LUC7L2, PIAS2, PRKAR1B, RBFOX1, and RPL19) interacts with at least one brain disease-associated gene." (PMID 26043779, 2015).
CROCC also shares sentences with these, for which no sentence is quoted: gallbladder cancer (2 papers); breast carcinoma (1); cataract (1); metabolic syndrome (1); Obesity (1); retinitis pigmentosa (1); Usher syndrome (1).